SYS1-DBNDD2 (SYS1-DBNDD2 readthrough (NMD candidate))
Synonyms: C20orf169-DBNDD2
Gene: Protein-coding gene on chromosome 20 (45,363,200 to 45,410,610, forward strand). Ensembl gene ENSG00000254806.
Genetic constraint (gnomAD): Missense variants: 93 observed, 92.73 expected, observed/expected ratio (o/e) 1, 90% interval 0.85 to 1.19. Synonymous variants: 50 observed, 42.12 expected, observed/expected ratio (o/e) 1.19, 90% interval 0.94 to 1.5.